SMAD2 (SMAD family member 2)
Diseases named in the same sentence as SMAD2 in open-access papers (continued):
Sharing a sentence is not in itself a finding about the gene and the disease.
cancer (continued). "In hESCs and other types of cancer cells, studies have demonstrated that Nodal drives signal transduction mainly via the Smad2/3 pathway." (PMID 25557170, 2015). "Conversely, Smad2 has also been shown to participate in the TGF-β1-induced EMT, since overexpression of constitutively active Smad2 enhances EMT in carcinoma cells in cooperation with H-Ras oncogene." (PMID 26078812, 2015). "Both in vivo and in vitro studies have identified SGPP1 and Smad2 as two novel targets of miR-27a, which is linked to STAT3 to regulate cancer cell proliferation, apoptosis and migration." (PMID 25166914, 2014). "A few recent studies have reported that Smad2, similar as Smad3 and Smad4, is mutant in cancers, but Smad2 plays differential roles from Smad3 and Samd4 in TGF-β signaling." (PMID 25166914, 2014). "The expression level of p-Smad2 in stromal fibroblasts ranged from 12.5% to 85.8%, and its expression level in cancer cells ranged from 19.3% to 94.2%." (PMID 25373709, 2014). "The analysis revealed that there was a positive correlation between the p-Smad2 expression level in stromal fibroblasts and the p-Smad2 expression level in cancer cells (χ2 = 4.176, P = 0.045)." (PMID 25373709, 2014). "There were 38.5% (30/78) and 92.3% (72/78) patients with high p-Smad2 expression in stromal fibroblasts and cancer cells, respectively." (PMID 25373709, 2014). "The present study demonstrated that p-Smad2 expression was confined to the nucleus, and its expression level in cancer cells was high in 72 (92.3%) of 78 NSCLC." (PMID 25373709, 2014). "There was a positive correlation between the p-Smad2 expression level in stromal fibroblasts and the p-Smad2 expression level in cancer cells (χ2 = 4.176, P =0.045)." (PMID 25373709, 2014). "The prognostic significance of p-Smad2 expression in stromal fibroblasts and cancer cells with regard to overall survival was determined by Kaplan-Meier." (PMID 25373709, 2014). "Taken together, these results indicate that the production level of TGFβ in cancer cells was significantly increased under hypoxia, and the expression levels of TGFβR and Smad2 phosphorylation were increased by hypoxia." (PMID 23690936, 2013). "The top scoring network (statistical score = 40, focus molecules = 24) for this set of 144 genes comprised of the SMAD family (SMAD2, 3, 4 &7) and others which are known to be involved in cancer and a host of Gastrointestinal diseases." (PMID 24204606, 2013). "Recently, a shift in phosphorylation of Smad2/3 from C-terminal to linker sites was demonstrated as a key event determining biological function of TGF-β in cancer." (PMID 22539990, 2012). "In Summary, the present study suggests that Smad2 is an important mediator to defend gastric cells from progressing towards poorly differentiated cancer." (PMID 22539990, 2012). "Whereas only 10 μM of SB-431542 decreases the nuclear level of phosphorylated Smad2 in Colo320 cancer cells, 50 μM of TGFRI inhibitor decreased the nuclear level of phosphorylated Smad2 in HT29NRP2 cancer cells." (PMID 21747928, 2011). "More specifically, Rac1 aids cancer cells to more efficiently antagonize TGF-β1/Smad3-mediated growth inhibition via its ability to promote Smad2 activation." (PMID 21624123, 2011). "Mutations in two Smad family member genes - SMAD4 (also known as MADH4, DPC4 &JIP) and SMAD2 (also known MADR2, and hMAD-2) have been identified in human cancers and more importantly with high frequency in pancreatic and CRCs." (PMID 20565773, 2010). "Several studies have reported different, in some cases, opposing transcriptional responses to activation of the canonical TGF-β/Smad2 pathway versus the alternative TGF-β/Smad1/Smad2 signal in normal and cancer cells." (PMID 20442782, 2010).
cancer (continued). "Having undergone EMT, others have shown that fibroblastoid carcinoma cells with elevated levels of activated Smad2 gain the capability to spread to a wide variety of tissues by a further increase in Smad2 expression." (PMID 20462450, 2010). "Only one missense mutation (2.8%), producing an amino acid substitution in the highly conserved region, and two homozygous deletions (5.5%) of the total coding region of the SMAD-2 gene were detected in the 36 cancers." (PMID 9820171, 1998). "The role of atorvastatin in cancer treatment is associated with its modulation of the EMT rather than direct inhibition of the TGF‐β/Smad2/3 signaling pathway." (PMID 39083441, 2025). "Notably, TGF-Beta pathway genes such as SMAD2, SMAD4, and TGFBR2 displayed differential mutation frequencies in all three cancers, suggesting a recurring pattern of dysregulation in this pathway among H/L patients." (PMID 40869017, 2025). "A higher proportion of cancer cells exhibited elevated expression of Smad2/3." (PMID 39941916, 2025). "In cancer cells, Smad2/3 preferentially regulates genes involved in cell proliferation." (PMID 39941916, 2025). "However, in cancer cells, despite a high Smad2/3 positivity rate of 90%, periostin expression was notably low at only 0.6%." (PMID 39941916, 2025). "Smad2/3 expression of CAFs and cancer cells was observed in 41.0% and 90.0%, respectively." (PMID 39941916, 2025). "Consequently, although Smad2/3 signaling is highly active in cancer cells, its target genes differ from those regulated by Smad2/3 in CAFs, such as periostin." (PMID 39941916, 2025). "This conclusion implies that the S417 could be a unique site for therapeutic interventions aimed at modulating SMAD2 activity in diseases associated with abnormal TGF-β signaling, such as cancer and fibrosis." (PMID 41044218, 2025). "In addition, within the phase I trial for SHR-1701, aggregated p-SMAD2 levels across all cancer subtypes (advanced solid tumors) showed a trend towards increased ORR with high baseline SMAD-2 levels." (PMID 39272905, 2024). "INHBA/TGFB1 complex activates SMAD2/3 and improves stem cell characteristics in cancer cells." (PMID 38881758, 2024). "However, Apc/Smad2 cis-compound heterozygous mice show rapid malignant progression of intestinal tumors to invasive cancer compared with Apc single heterozygous mice." (PMID 38569937, 2024). "Significant TFs identified within the enhancer regions include SMAD2:SMAD3, EWS-ERG fusion, TWIST1, and TEAD3, which play important roles in regulation of transcription in transforming growth factors and embryonic development and are associated with cancers." (PMID 36936794, 2023). "LincRoR has been shown to modulate cancer progression via interaction with microRNA-145, and microRNA-145-5p was shown to ameliorate hypertrophic scar through suppression of myofibroblast activation and reduction of Smad2/3." (PMID 36986051, 2023). "In the current study, we report the function of LncRNA SNHG1 in TGF-β/SMAD2 signal way regulation in cancer development, which was similar with the previous study, indicating that the LncRNA SNHG family may regulate CRC progression in a similar way." (PMID 35310912, 2022). "Similar results were obtained for cancer-associated fibroblasts (CAF), in which TEVs-induced SMAD2/3 nuclear translocation could be blocked by pre-treatment with TβRI kinase inhibitors." (PMID 35915084, 2022). "Moreover, ZEB2 correlates with SMAD1 in 28 cancer types, SMAD2 in 27 cancer types, SMAD3 in 22 cancer types, SMAD5 in 28 cancer types, CTBP1 in 14 cancer types, and CTBP2 in 22 cancer types." (PMID 35723302, 2022).
cancer (continued). "However, the mechanisms responsible for the selective activation of SMAD2 versus SMAD3 during cancer progression are still poorly understood." (PMID 35681731, 2022). "In general, L-theanine could induce cancer cell apoptosis through the mitochondrial pathway, inhibiting the EGFR, NF-κB, and other signaling pathways, downregulating MMP9, or upregulating Smad2 in cancer treatment." (PMID 35445053, 2022). "SMAD2/TGF-β1 signaling also has an important role in cancer, including in CRC." (PMID 35587159, 2022). "In addition, recent studies suggest the use of SMAD2/3 expression or activation level as a prognostic marker in various cancers." (PMID 35681731, 2022). "Our results demonstrated that rhoifolin significantly inhibited the TGF-β2/SMAD2 signaling pathway in pancreatic cells, which may contribute to its inhibitory effect on cancer cell migration and invasion." (PMID 35383226, 2022). "SMAD2 has been shown to trigger the upregulation of various lncRNAs to promote cancer." (PMID 33511320, 2021). "Some studies showed that SMAD2 promotes cancer metastasis, resulting in poor survival of patients." (PMID 34048444, 2021). "Smad2/3 is a known modulator of EMT in cancer and is also known to be flow responsive." (PMID 34641959, 2021). "miR-132-3p directly targeted SMAD2 and suppressed cancer progression." (PMID 33511320, 2021). "We have shown that HAPLN1 overexpression in cancer cells restored p-Smad2/3 to control levels, indicating that HAPLN1 may regulate the TGF-β signaling pathway." (PMID 34966673, 2021). "Other interesting examples included AGO4, LIN28A and SMAD2 overmutated in BLCA (an otherwise extremely low-mutation cancer with no mutations in other genes); LIN28B overmutated in SKCM; PRKRA overmutated in OV; and DDX5 overmutated in BRCA and KIRP." (PMID 33406242, 2021). "Importantly, inhibition of either FA uptake by CD36 blocking antibodies or FA mitochondrial metabolism by CPT1 inhibitor etomoxir significantly reduced Smad2 acetylation in 6.5/cancer cells." (PMID 31974393, 2020). "Moreover, we identified a highly positive correlation of two circRNAs generated from the SMAD2 gene, a known cancer gene listed in CGC." (PMID 32353949, 2020). "Moreover, it has been demonstrated that leptin can be a co-factor for TGF-β in cancer using an in vitro model of kidney fibroblasts whereby leptin treatment enhances SMAD2/3 phosphorylation by TGF-β32,33." (PMID 32968152, 2020). "SMAD2 phosphorylation can promote the occurrence of cancer and increase cell resistance." (PMID 33033505, 2020). "In addition, transcription level of SMAD2 was significantly increased in 17 types of cancer tissues, which indicated that SMAD2 had low cancer specificity." (PMID 33202380, 2020). "c-Myc directly associates with the MH2 domain of SMAD2 and SMAD3 to inhibit the TGF-β-induced transcriptional activity of Sp1 and SMAD/Sp1-dependent transcriptions of the p15Ink4B gene and eventually promotes cell growth and cancer progression." (PMID 32340410, 2020). "SMAD2 has been reported to be abnormal expression in many cancers." (PMID 32226309, 2020). "Furthermore, pan-cancer analysis revealed that an enhanced expression of SMAD2 was detected in most cancers, and the SMAD2 related signaling pathways were activated as well." (PMID 33202380, 2020). "Importantly, we noticed that p-Smad2 also is present in the nearby CD68- cancer cells (within dash line)." (PMID 32724475, 2020). "Based on the observation of upregulated EMT and associated key signature genes such as TGFB2, TGFBR2, SMAD2, and ZEB1 in the high-risk patients, we infer that m6A regulatory machinery must interact with EMT to regulate cancer metastasis in various human malignancies." (PMID 31069256, 2019). "The activation of LKB1/AMPK inhibits the migration of TGF-β–stimulated cancer cells by inhibiting Smad2/3 activity, which suggests that AMPK may be a target for cancer drug therapy." (PMID 31126310, 2019).
cancer (continued). "The expression of miR‐524 can restrain the proliferation of cancer cell via targeting and inhibiting the expression of Smad2, Hes1, and Tead1 which are essential proteins for transforming growth factor‐β (TGF‐β), Norch, and Hippo signaling pathways, respectively." (PMID 30643726, 2019). "FHL1 acts in activation of the tumor suppressor gene p21 and repression of the oncogene c-myc through physically and functionally interacting with Smad2, Smad3 and Smad4 that are important regulators of cancer development and progression in a casein kinase 1δ-dependent manner." (PMID 30379883, 2018). "In addition, SMAD7 has been proved to suppress TGF-β/Smad activity by binding SMAD2/3 and prevent their activation upon TGF-β1 stimulation in cancer-associated fibroblasts (CAFs) formation." (PMID 30154401, 2018). "We thereby hypothesized that the presence of inhibin α in the environment led to a functional switch of cancer-secreted inhibin βA from activin-mediated SMAD2/3 activation to inhibin-mediated suppression." (PMID 30348200, 2018). "TGFβ1/Smad2/3 cascade signaling plays an important role in the EMT of cancer cells." (PMID 30174709, 2018). "In addition, we previously demonstrated that LRG enhances TGF-β-induced Smad2 phosphorylation in several cancer cell lines." (PMID 28615031, 2017). "Multiple miRNAs regulate PTEN, FOXO1 and SMAD2, resulting in cancer progression." (PMID 29069829, 2017). "In highly resistant spherical cancer cells, which results from enhanced self-renewal via cyclin D1 and cyclin D1-dependent activation of Smad2/3 and Smad4, inducing differentiation with Smad inhibitor is a critical tactic for turning resistant CSCs into therapy-sensitive cells." (PMID 28415588, 2017). "Interestingly, double immunofluorescence staining showed that B7-H4 is coexpression with EMT-related markers, including p-Smad2/3, Snail and Vimentin, in carcinoma cells." (PMID 29190910, 2017). "In addition, miR-148a was also found to inhibit cancer metastasis by suppressing TGFβ-induced EMT through SMAD2, its direct functional target in human gastric cancer." (PMID 27187371, 2016). "SERPINE1 is fundamentally located in extracellular region of cell and plays important roles such as protease binding in which is mainly involved in chronological cell aging and angiogenesis, complement and coagulation cascades and loss of function of SMAD2 and SMAD3 in cancer." (PMID 28228815, 2016). "Moreover, this miRNA was shown to attenuate cancer stem cells (CSCs)-like properties through the inhibition of TGF-β/SMAD2 signaling pathway upon treatment with Glabridin." (PMID 27187371, 2016). "According to these studies, Smad2 linker phosphorylation (on residues 245, 250 and 255) correlates with fibrotic EMT, while Smad2 (on residue 220) and Smad3 (on residue 179) linker phosphorylation correlate with the invasive behavior of fibrotic liver cells that progress to carcinoma development." (PMID 27367735, 2016). "In addition to Smad2 and cancer invasion, our work revealed a novel regulatory function of hsa-miR-140-5p in CSC and autophagy." (PMID 25980495, 2015). "A generally high p-Smad2/3 activity suggests a major role of the pathway in many cancer types." (PMID 26450853, 2015). "It has been reported that TGF-β induces autophagy in cancer cells through Smad2/Smad3 signaling pathway, and autophagy is an essential metabolizing process for CSC origin and maintenance, we reasoned that hsa-miR-140-5p may impact the colorectal CSC survival." (PMID 25980495, 2015). "Moreover, we also found that there was a positive correlation between the p-Smad2 expression level in stromal fibroblasts and the p-Smad2 expression level in cancer cells (P = 0.045)." (PMID 25373709, 2014). "The new signal pathway of miR-27a-Smad2-TGF-β could also contribute to the inhibitory role of miR-27a on cancer cell migration, invasion and metastasis, detailed mechanism is under investigation." (PMID 25166914, 2014).
cancer (continued). "Yet another mode may be Wnt3a promoting a cancer-associated fibroblasts-like phenotype in fibroblasts, partially through the TGF-β/Smad2 signaling activation by a β-catenin-dependent mechanism, indicating that Wnt and TGF-β signaling are linked by Smad." (PMID 24427302, 2014). "In the present study, therefore, we investigated the p-Smad2 expression in surgical resection specimens from NSCLC to evaluate the prognostic significance of p-Smad2 expression in stromal fibroblasts and cancer cells for patients with clinical stage I to IIIA NSCLC." (PMID 25373709, 2014). "Furthermore, we identified that HRG-β1 induced cancer cell migration and invasion through Smad2 activation by wound healing assays and matrigel invasion assays." (PMID 23937725, 2013). "The role of Smad2 during formation and progression of different cancer type remains controversial." (PMID 22539990, 2012). "It remains to be determined whether epidermal specific Smad3 deletion will have similar or distinct effects on cancer development as the Smad2 epidermal null." (PMID 23326666, 2012). "Moreover, NRP1 associates with TGFRI and TGFRII to enhance TGFβ1 signaling in cancer cells, augmenting canonical Smad2/3 signaling." (PMID 21747928, 2011). "Phospho-Smad2 was mainly immunolocalized in the nuclei of cancer cells." (PMID 21110833, 2010). "As Smad2/3 signalling is involved in several functions, from ES cell pluripotency to differentiation towards lineages including endoderm, and in diseases like cancer, our system and results will be useful to a range of scientists addressing diverse subjects." (PMID 19172185, 2009). "However, resistance to TGF-β in cancer may occur through several mechanisms such as reduced expression of TβRI and/or TβRII, mutations or functional inactivation of TβRII, inactivating mutations in Smad2 and Smad4 and overexpression of inhibitory proteins including Smad7." (PMID 16251876, 2005). "However, in the cancer microenvironment, a high level of TSP-2 produced by cancer-associated fibroblasts is activated via the TGF-β1/Smad2/3 pathway, binds to integrin αvβ3/CD36 and activates the MAPK pathway in cancer cells to promote tumor growth and adhesion." (PMID 38516004, 2024). "Notably, the copy numbers of cancer-associated genes such as KRAS, ETV1, and SMAD2, displayed a subtype-specific increase in prevalence and magnitude along PDAC progression, highlighting the importance of matched primary and metastatic samples for uncovering such patterns." (PMID 38702773, 2024). "Likewise, it would be interesting to assess how our observed high SMAD2-driven poor response to MEK inhibition in fibroblasts may contribute to the resistance to MEK inhibitors in cancer." (PMID 36572730, 2023). "Moreover, the repression of protein SMAD2 could lead to malignant transformation of tumors owing to abnormal expression of genes related to cancer cell apoptosis." (PMID 35164166, 2022). "Thus, we speculate that HOXB9 may activate TGFβ/Smad2 signalling, which in turn alters a panel of downstream target genes involved in cancer cell invasion and metastasis." (PMID 34247196, 2021). "Increases in TGF-β2 mRNA and protein could be recapitulated by 12–24 h exposure of native cancer cells to acidic pH 6.5 and further evidence of the activation of TGF-β2 signaling pathway in acidosis-adapted cancer cells was obtained by documenting an increase in the extent of phospho-Smad2/3." (PMID 31974393, 2020). "However, it is controversial for the functional roles of SMAD2 in cancer." (PMID 32226309, 2020). "Notably, the phosphorylation of Smad2 is the most important step for this factor to control its function, and this explains that the vast majority of cancers with an impaired Smad2 action have only a dysregulated Smad2 phosphorylation and do not present a matched SMAD2 driver gene mutation." (PMID 31387321, 2019).